SMO (smoothened, frizzled class receptor)
Diseases named in the same sentence as SMO in open-access papers (continued):
Sharing a sentence is not in itself a finding about the gene and the disease.
tumor (continued). "Similarly, Vasohibin 2 (VASH2) protein suppresses pancreatic CSCs through decreasing SMO and Gli1/2, while also functioning as a tumor promoter, stimulating resistance to doxorubicin (DOX) upregulating pancreatic CSCs via the Hh and Notch pathways." (PMID 37305676, 2023). "As Aurora kinase B is a mitotic kinase that regulates chromosome segregation and cell cycle progression during mitosis, dual treatment with a SMO inhibitor and Aurora B/C kinase inhibitor might target both ciliated and mitotic tumor cells." (PMID 36394953, 2023). "Furthermore, the knockdown of PCSK9 decreases the expression of SMO, and its colocalization with cholesterol at the cell membrane leads to the inhibition of tumor progression." (PMID 37151886, 2023). "Additionally, SHH, GLI1, and SMO overexpression were significantly correlated with tumor recurrence and shorter disease-free survival (DFS)." (PMID 37626893, 2023). "Although SMO inhibitors display promising tumor‐suppressive effect, resistance development may possibly be related to the overactivation of upstream signaling pathways." (PMID 37846367, 2023). "BCC tumour cells often acquire resistance to SMO inhibitors, which may result from a cell identity switch towards a mesenchymal-stem-cell-like phenotype." (PMID 36612301, 2023). "Interestingly, there is a record of the G453S mutation in SMO in the COSMIC database, suggesting that human tumours can also acquire resistance specifically to this drug." (PMID 36294790, 2022). "This conclusion opens up a question as to whether reintroducing cilia can be a strategy to reset the Hh signaling and resensitize tumor cells to SMO inhibitors." (PMID 35163655, 2022). "In this regard, Vismodegib, one of the SMO antagonists, appears to downregulate the expression level of Gli1, Hedgehog Interacting Protein (Hhip), and Ptch1 especially in the stroma to suppress HH signaling and tumor growth." (PMID 35501851, 2022). "Finally, RAS/MAPK activation drives resistance to SMO inhibitors as well as tumor evolution and metastasis in Hh-dependent cancer." (PMID 35163655, 2022). "Pharmacological activation of SMO receptor using SAG (SMO agonist) increased HHIP-AS1 expression in two independent tumor cell lines, Daoy and CHLA-266, and one primary cell culture, HHU-ATRT1 as well as in non-tumor cells with SHH activation, namely neuronal stem cells (NSC)." (PMID 35831316, 2022). "Due to the role of Hh pathway in MPM, and the poor response to SMO/Hh inhibitors in this tumor, here, we hypothesized that Hh can be controlled by both SMO-dependent and SMO-independent mechanisms." (PMID 36358635, 2022). "Second, SMO inhibition is an effective strategy to reduce MMe tumor growth." (PMID 35501851, 2022). "To assess alternative pathways that may drive BCC tumor growth, we reanalyzed our bulk-level RNA-sequencing (RNA-seq) data of 14 matched tumor-normal pairs of advanced and SMO inhibitor-resistant BCC samples." (PMID 34268113, 2021). "After receiving treatment with vismodegib for a total of 28 months, molecular analysis of tumor tissue revealed a mutation in PTCH1 but no mutation in SMO." (PMID 34611482, 2021). "These evidences underline as SMO antagonists encapsulated in NPs drug delivery system for the treatment of SHH-MB, could improve their ability to target the specific tumor site at optimal therapeutic concentration, thus mitigating their toxic effects." (PMID 34164380, 2021). "In such circumstances, correlative analyses of potential biomarkers with tumor responses may help identify a subset of patients who may derive benefit from SMO inhibitors." (PMID 34572373, 2021). "Since the HH pathway contributes to the development of the dense stromal tissue, several studies combined SMO inhibitors with either cytotoxic chemotherapeutic drugs or a targeted antibody to increase the delivery of the drugs and promote tumor infiltration of the CD8 T cells." (PMID 34440799, 2021).
tumor (continued). "Mechanisms of resistance include mutations in SMO, noncanonical cell identity switching leading to tumor cell resistance, and non-canonical pathway crosstalk causing Hedgehog pathway activation." (PMID 34611482, 2021). "Additionally, several tumor entities are driven by SMO-independent GLI activity and thus display a priori SMOi resistance." (PMID 34439381, 2021). "Furthermore, IHC assays revealed that GNG7 overexpression resulted in distinct suppression of Hedgehog signaling pathway-related molecules (GLI1, PTHCH1 and SMO) in tumor tissues obtain from xenograft tumor model." (PMID 34635014, 2021). "SMO expression affects tumor size, lymph node involvement, and tumor recurrence." (PMID 31979397, 2020). "SMO expression correlates with tumor size, invasiveness, metastasis and recurrence." (PMID 32962123, 2020). "PTCH1 is typically described as a tumor suppressor by virtue of its inhibitory action toward SMO." (PMID 32957513, 2020). "The SMO expression has been related to prognosis and tumor status in CRC patients." (PMID 33489917, 2020). "Aberrant activation of the Hh signaling pathway by mutations in pathway components such as PTCH, SUFU, SMO, and amplifications of GLI1 and GLI2 drive tumor growth in basal cell carcinoma (BCC), medulloblastoma, keratocystic odontogenic tumors, meningioma, and ameloblastoma." (PMID 32108165, 2020). "Moreover, inhibition of SMO by cyclopamine, a specific inhibitor of SMO, or by genetic invalidation of SMO, prevented cell proliferation in vitro and tumor growth in vivo." (PMID 32110934, 2020). "Nonsense mutations are often not directly associated with RNA decay, however RNA-seq analysis showed significant upregulation of downstream transcripts in the SMO-SUFU-GLI pathway, including those encoding MDM2 and IGFBP6, which are associated with tumor proliferation." (PMID 31023376, 2019). "However, the response to SMO inhibitors were variable in these studies, likely reflecting tumour heterogeneity." (PMID 31362788, 2019). "We investigated the impact of the SMO-FGFR crosstalk on tumor growth and invasiveness in MB." (PMID 31835472, 2019). "Pharmacological and genetic inhibition of GLI function is more effective in reducing tumor proliferation and inducing apoptosis than the inhibition of the canonical pathway at SMO level, suggesting that GLI activity is crucial for RAS/MEK-induced colon cancer proliferation." (PMID 31244888, 2019). "Treatment of engrafted mice with the SMO inhibitor vismodegib reduced immunosuppressive immune cell populations such as MDSCs, M2 macrophages and Treg cells in the tumor lesions, while it increased the number of cytotoxic CD8+ T-cells and M1 macrophages, resulting in less metastasis." (PMID 31878932, 2019). "In TNBC, a correlation between SMO expression and histological grade and tumor stage was reported." (PMID 31027259, 2019). "GDC-0449 (vismodegib), which acts by binding to the extracellular domain of SMO and antagonizing Hh signaling, has shown promising anti-tumor activity in advanced BCC and became the first Hh signaling inhibitor approved by the FDA in 2012 for the treatment of metastases and locally advanced BCC." (PMID 31775795, 2019). "First evidence for such immunosuppressive mechanisms in BCC came from studies of murine BCC models showing that transforming growth factor beta (TGFβ) secreted by oncogenic SMO-expressing keratinocytes is able to reduce the number of effector lymphocytes in the tumor tissue." (PMID 31878932, 2019). "Interestingly, cholesterol is required for HH pathway signal transduction in MBSHH cells and statins, inhibitors of cholesterol biosynthesis block HH activity in MB cells and synergize with SMO inhibitors to decrease tumor cell growth." (PMID 30279357, 2018). "Therefore, there is a need for new SMO antagonists able to effectively inhibit tumor growth and CSC self-renewal, while avoiding drug resistance mechanisms." (PMID 29396391, 2018).
tumor (continued). "Whether canonical HH signaling through SMO in pancreatic fibroblasts suppresses or promotes tumor cell growth remains controversial." (PMID 30456390, 2018). "Furthermore, tumor growth inhibition correlated with Gli1 expression levels, which suggests that Gli1 is a perfect biomarker for the antitumor effects of SMO inhibitors in Ptch mutant ERMS." (PMID 30319965, 2018). "The issue that confronted investigators studying SMO inhibitors was that there were no tumour cell lines available in which activating HH pathway mutations had been documented and elevated HH pathway activity had been demonstrated." (PMID 30068568, 2018). "In resistant tumours lacking activating mutations in SMO, they found that GLI1 participates in a complex with SRF and MKL1 which promotes enhanced transcription of HH pathway target genes." (PMID 30068568, 2018). "Some tumor types depend on mutations of specific pathway components such as PTCH1, SMO and SUFU." (PMID 30158435, 2018). "However, under strong PDEs inhibition, the systems became more sensitive to both SMO and PI3K, but PI3K became more relevant than SMO for controlling tumour proliferation." (PMID 29776351, 2018). "Whether SMO is released in ciliary vesicles and whether this release impacts tumor cell proliferation will require further study." (PMID 30410731, 2018). "In summary, these data demonstrate that in vivo treatment of Ptch mutant ERMS with SMO inhibitors and/or pictilisib either stop or reduce tumor growth and that sonidegib monotherapy or a HhAntag/pictilisib combination therapy show the strongest antitumor effects." (PMID 30319965, 2018). "The controversy was addressed in an exhaustive analysis carried out by de Sauvage and co-workers at Genentech Inc., using a more potent, and less toxic, SMO inhibitor termed HhAntag, in addition to cyclopamine, to investigate paracrine and autocrine HH pathway signalling in tumour cells." (PMID 30068568, 2018). "Finally, in an orthotopic rat CCA model, the presence of PDGF-BB in myofibroblasts and PDGFR-β in CCA cells were confirmed, and after cyclopamine administration (a SMO inhibitor), tumor apoptosis increased and tumor size and weight decreased." (PMID 30249019, 2018). "Inhibition of SMO has been studied in a variety of tumor types." (PMID 29642386, 2018). "The most significant take-home message from this review is that there is a lack of compelling preclinical evidence supporting the use of SMO inhibitors in a broad class of tumours lacking mutations in HH pathway genes." (PMID 30068568, 2018). "Amplification of chromosomal regions containing GLI2 was also found in a model of vismodegib resistance, as well as in two of three sonidegib-resistant MB tumors, in which the increased expression of GLI2 mRNA has been shown to mediate tumor growth independently from SMO." (PMID 30558232, 2018). "Therefore, understanding the precise mechanisms of HH pathway regulation in the tumor microenvironment is important to advance new therapeutic strategies for SMO inhibitor-resistant BCC." (PMID 29615568, 2017). "Cyclopamine has anti-tumour properties via their direct binding to SMO." (PMID 28978035, 2017). "In cases of primary resistance in the tumor tissue of origin, given the cost of treatment with SMO inhibitors as compared with genetic sequencing, it may be more cost-effective for all patients to undergo screening prior to the initiation of targeted therapy." (PMID 29259776, 2017). "Mechanisms of resistance could be associated with SMO mutations and amplification of GLI2, underlining the importance of this transcription factor for sustained tumor growth." (PMID 28418873, 2017).
tumor (continued). "This could be of particular relevance in tumours that express aberrant levels of Gli1 or that are otherwise activated downstream of Patched proteins and are thus resistant to the SMO inhibitor Vismodegib." (PMID 27621083, 2016). "In rare instances, we found scattered mCherry-positive L0 control cells that were located outside of the primary tumor mass and stained positively for gamma-tubulin and SMO, observations suggesting that the cilia of these L0 cells were responding to SHH within the brain environment." (PMID 26760767, 2016). "Interestingly, it has been shown that oxysterols (OHCs), oxygenated derivatives of cholesterol, can enhance the activity of Smoothened (SMO), a member of Hh pathway, and contribute to tumour progression." (PMID 25761781, 2015). "To determine whether SMO inhibition combined with NFκB inhibition is more effective in inhibiting tumor growth, we performed an identical experiment in mice treated with cyclopamine." (PMID 26413810, 2015). "Inappropriate Hh signaling has been ascribed to either ligand-dependent, i.e. autocrine and/or paracrine signaling, or ligand independent tumor cell intrinsic pathway activation due to loss-of-function mutations in PTCH or SUFU and gain-of-function mutations in SHH, SMO or GLI1/2." (PMID 26053182, 2015). "However, the tumor recurred and analysis of the patient’s tumor cells revealed the presence, in addition to the initial PTCH1 mutation, of a mutant SMO (SMO-D473H)." (PMID 25008045, 2014). "Sequencing results showed that one patient had a tumor harboring the CTG insertion in the SMO gene." (PMID 23826113, 2013). "Thus, there is a need for molecules that act downstream of SMO in the HH signalling pathway and that inhibit HH signalling specifically in tumor cells." (PMID 21143927, 2010). "Results demonstrated significant inhibition of tumor growth SMO shRNA versus control shRNA." (PMID 20067614, 2010). "Therefore, confirming SMO expression in both the primary tumor and any metastases might be beneficial when considering Hh inhibition as a treatment strategy for SEB and SCC." (PMID 40542075, 2025). "Furthermore, a greater histological grade of the tumour was associated with overexpression of GLI1, GLI2, PTCH1 and SMO, which may indicate a critical function for Hh signalling in HNSCC malignancy." (PMID 39234399, 2024). "For instance, a preclinical study demonstrated the efficacy of saridegib, a Smoothened (SMO) inhibitor pivotal for the hedgehog pathway, in diminishing stromal compartments within tumors and increasing the density of blood vessels within the tumor core by targeting CAFs." (PMID 38443595, 2024). "Moreover, low expression of GLI1 was detected in the non-neoplastic oral mucosa near the tumour, and the clinical stage of the patients was also closely linked with the expression level of SMO." (PMID 39234399, 2024). "Additionally, DNMT1 pharmacological inhibition alone and in combination with SMO inhibition effectively inhibits tumor growth in murine and human SHH-MB cell models and prolongs survival of SHH-MB mouse models by inhibiting SHH signaling output downstream of SMO." (PMID 39107797, 2024). "When tested in vivo, dactolisib could reduce tumor volume, vascularity and metastasis and improve animal survival, especially when combined with other drugs, such as topotecan, carboplatin, vincristine or the SMO inhibitor LDE225." (PMID 36839989, 2023). "In addition, the AURKA inhibitor could rescue ciliogenesis and reverse the acquiring resistance to sonidegib (SMO inhibitor) of tumor cells due to PC deficiency, revealing the essential role of AURKA on tumor cell PC formation." (PMID 37101292, 2023). "Furthermore, overexpression of GLI1, GLI2, PTCH1, and SMO was correlated with a higher histological grade of the tumor, what may suggest that HH signaling plays a key role in HNSCC malignancy." (PMID 37626893, 2023). "In addition, the expression of SMO directly correlates with HCC tumor size." (PMID 35464958, 2022).
tumor (continued). "The effect of SMO antagonists in tumour stroma is largely unknown." (PMID 34831015, 2021). "Mechanisms of resistance to HHIs include mutations in SMO, noncanonical cell identity switching resulting in resistant tumor cells, and non-canonical pathway crosstalk that may activate the Hedgehog pathway." (PMID 34611482, 2021). "Thus, one compound (4s) that is structurally simpler than other available SMO antagonists on the market showed the highest cytotoxic effect (IC50 of 1.3–15 μM) in all tumour cell lines and was equally effective in both HH-dependent and independent cell lines assayed." (PMID 34445078, 2021). "It would be interesting to know whether tumor aggressiveness correlated with the presence or absence of PTCH1 or SMO with FBXW7 mutations." (PMID 34518642, 2021). "Moreover, patients who developed resistance to a SMO inhibitor may continue to experience tumor progression also in response to other SMO inhibitors." (PMID 34639065, 2021). "Pre-clinical studies in transgenic mouse model showed that SMO inhibitors, such as saridegib were able to reduce the density of desmoplastic stroma in pancreatic cancer tissue and increase gemcitabine delivery to the tumor, due to increased intra-tumoral mean vessel density." (PMID 31035664, 2019). "Thus, targeting PTCH1-mutant PF cells with a SMO inhibitor resulted in tumor cell death." (PMID 31362756, 2019). "Lack of any significant association of SMO expression among tumour and controls were observed." (PMID 29329585, 2018). "The findings suggest that MKL1 inhibitors may be effective in treating a subset of HH pathway tumours that are resistant to SMO inhibitors and they imply that the combined use of SMO inhibitors and MKL1 inhibitors should be considered for the treatment of naive tumours." (PMID 30068568, 2018). "Similarly, in a mouse model of mutant K-Ras-induced pancreatic tumorigenesis, SMO deficiency does not alter tumor formation." (PMID 30558232, 2018). "Tumor-derived HH ligands, such as sonic hedgehog (SHH), bind to their cognate receptor Patched1 (PTCH1) on stromal fibroblasts, releasing its repression of Smoothened (SMO) and allowing for activation of downstream glioma-associated oncogene homolog (GLI) transcription factors." (PMID 30456390, 2018). "In a small case report series, 3 patients with NSCLC with Hh pathway activation had been treated with the SMO inhibitor sonidegib with a significant reduction in tumor burden, suggesting that Hh pathway alterations occur in NSCLC and could be an actionable and valuable therapeutic target." (PMID 28416737, 2017). "Importantly, the presence of these ncRNAs was independent of BRAF-V600E and SMO-L412F mutations, histology type or tumour location, but was positively correlated with the tumour size." (PMID 27965463, 2017). "The iG2 may be used in tumor that resists to SMO inhibitors." (PMID 27465044, 2016). "These analyses revealed that AMF directly targets smoothened (SMO) to disrupt the SHh signaling pathway, thereby suppressing RB stem cell (RBSC) self-renewal and tumor progression." (PMID 42305888, 2026). "Inhibition of C1GALT1 using a genetic or pharmacological inhibitor, such as ITZ, reduces SMO O-glycosylation, Hh signaling, and EWSR1::FLI1 expression, resulting in decreased ES cell viability and tumor growth in mice." (PMID 39894896, 2025). "We detected the protein level of HER2 and SMO to analyse the correlation between the HER2 and SMO expression, and the tumour growth." (PMID 40426308, 2025). "In a mouse model of small cell lung cancer (SCLC), constitutive SMO activation drove tumor initiation and progression, whilst treatment of SCLC cells with a SMO inhibitor suppressed cell growth." (PMID 40301543, 2025).